YTHDC1 (YTH N6-methyladenosine RNA binding protein C1)
Diseases named in the same sentence as YTHDC1 in open-access papers (continued):
Sharing a sentence is not in itself a finding about the gene and the disease.
tumor (continued). "Human MGC803 GC cells were transfected with a lentiviral vector to knock down YTHDC1 expression (kd-YTHDC1), and added to a matrix gel, prior to subcutaneous injection in nude mouse skin; then, subcutaneous tumor generation was found 2 weeks later." (PMID 38573528, 2024). "Here, we demonstrate that upregulated KAP1 by MYCN interacts with YTHDC1 and protects YTHDC1 from ubiquitination and degradation, leading to enhanced tumor cell proliferation." (PMID 38745192, 2024). "This molecule is enriched in the nuclear speck on the Cell Component (CC) and existing studies on the role of YTHDC1 in tumors indicate that YTHDC1 maintains the structure and function of the nuclear speck, which regulate tumor cell genesis and metastasis." (PMID 38600232, 2024). "The IHC and western blot results showed that both GL‐1 and GC‐7, as DHPS inhibitors, inhibited METTL3, YTHDF2, and YTHDC1 in tumor tissues." (PMID 38952061, 2024). "Overall, the METTL3/PAX8/YTHDC1 axis has been revealed to play a pivotal role in repressing tumour occurrence, and is antagonized by miR-493-5p." (PMID 38993572, 2024). "4-6 weeks later, YTHDC1 upregulation significantly suppressed the growth of the tumor as compared to the control group." (PMID 37781028, 2023). "Boosting YTHDC1 levels slowed tumor cell growth by decreasing levels of GLUT3, a glucose transporter that accelerates sugar input to cancer cells." (PMID 37258572, 2023). "Tumor m6A research has recently gained attention, and the levels of FTO, METTL3, and YTHDC1 were significantly higher in the high-risk group compared to the low-risk group." (PMID 36968601, 2023). "In a cohort of patients with 51 tumour sections and 37 sections of adjacent normal tissues, low YTHDC1 level was detected in malignant tumour by IHC assay, as well as in 16 paired tumour/peri‐tumour samples by quantitative real‐time PCR." (PMID 37070134, 2023). "The results demonstrated that YTHDC1 was significantly and positively correlated with BMI1 and SOX2 mRNA expression levels in HNSCC tumor cells, and that cells with high YTHDC1 expression coexpressed stemness pathway-related genes." (PMID 36411870, 2022). "In conclusion, our findings reveal a role for YTHDC1 in regulating the tumor stem cell pathway in HNSCC." (PMID 36411870, 2022). "In summary, our work identifies m6A reader YTHDC1 as the fulcrum of tumor suppressor RBM4 oncogenic switch and reveals a previously unappreciated role of nuclear AURKA in regulating RNA splicing." (PMID 35361747, 2022). "In turn, AURKA links the interaction between hnRNP K and YTHDC1, thereby enhancing the production of tumor-promoting isoform RBM4-S." (PMID 35361747, 2022). "Subsequently, we analyzed single-cell transcriptomic analysis data to verify the correlation between YTHDC1 and tumor stemness." (PMID 36411870, 2022). "Consistent with previous findings, YTHDC1 is downregulated in ccRCC tissues and functions as a tumor-inhibiting protein." (PMID 35974388, 2022). "Blue background indicated the most significant genes down-regulated in tumor tissues, including YTHDC1, YTHDC2, METTL16, and FTO." (PMID 35581263, 2022). "YTHDC1 mRNA was abnormally upregulated in HNSCC tumor tissues compared to normal tissues according to TCGA data." (PMID 36411870, 2022). "Mass spectrometry data from the Clinical Proteomic Tumor Analysis Consortium (CPTAC) showed that primary tumors express YTHDC1 protein at significantly higher levels compared to normal cells." (PMID 35966596, 2022). "Subsequently, YTHDC1 gene suppression assays were performed in HNSCC cell lines to investigate the effect of YTHDC1 on tumor cell stemness maintenance, proliferation, and migration capacity." (PMID 36411870, 2022). "An in vivo rescue experiment was performed and we observed that overexpressing SMAD3 in MDA-MB-231 YTHDC1 KO cells restored metastasis in the lungs, with little effect on primary tumor size." (PMID 35966596, 2022).
tumor (continued). "Collectively, our in vivo animal model data support a tumor-promoting role for YTHDC1, which is consistent with clinical evidence." (PMID 35966596, 2022). "YTHDC1 expression levels were significantly upregulated in SCC9 spheres, and YTHDC1 was aberrantly expressed in HNSCC tumor tissues." (PMID 36411870, 2022). "Taken together, TIMER analysis indicated that METTL14, ZC3H13, and YTHDC1, as key regulators of m6A modifications, were closely related to tumor immune infiltration in EC." (PMID 34230220, 2021). "Compared to the normal tissue, TRMT10C, TRMT6 and YTHDF2 were relatively highly expressed in the tumor tissue, while YTHDC1 was relatively less expressed." (PMID 34777359, 2021). "YTHDC1, a member of RNA methylation modification binding proteins, plays critical roles in tumor occurrence and metastasis." (PMID 34897032, 2021). "With TCGA cohort, we examined the four common m6A readers (YTHDF1, YTHDF2, YTHDF3, and YTHDC1) in LUAD tumor samples and normal samples, and found YTHDF1 highly expressed in tumor tissues." (PMID 32195181, 2020). "Differential expression analysis indicated that the protein expression levels of KIAA1429, RBM15, HNRNPC, HNRNPA2B1, YTHDF1, YTHDF2, and YTHDC1 were higher in tumor samples than in non-tumor samples." (PMID 32582536, 2020). "YTHDF1 and YTHDC1 followed it, showing subgroup-to-group expression varieties in 21 and 19 tumor types." (PMID 33585244, 2020). "Additionally, increased NAT10 expression promotes glycolysis in tumor cells by stabilizing YTHDC1, PFKM, and LDHA mRNA, thus providing essential energy support for tumor growth." (PMID 39897026, 2025). "Additionally, YTHDC1 has been reported to inhibit tumor development by regulating mitochondrial energy metabolism in tumor cells." (PMID 39827178, 2025). "Moreover, IHC staining was performed on the subcutaneous tumor tissues of mice in which YTHDC1 was downregulated, and it was found that OIP5 expression was lower in the kd-YTHDC1 group, while GPD1L expression was increased." (PMID 38573528, 2024). "Thus, these nuclear bodies induced by m6A-modified mRNA and YTHDC1 LLPS are crucial regulators for tumor cell survival and differentiation repression." (PMID 39239525, 2024). "In the tumor orthotopic transplantation experiment, the survival analysis of the nude mice showed that the individual knockdown of YTHDC1, POLR2B, or PBX1 could prolong survival." (PMID 39090090, 2024). "The potential variation in the functionality of YTHDC1 across tumors could potentially be attributed to its varying expression patterns within specific tumor types and its influence on unique sets of downstream target genes." (PMID 38565940, 2024). "Furthermore, YTHDC1 overexpression treatments significantly restored in vivo tumor growth compared with the Lenti-shNAT10 group." (PMID 38233839, 2024). "IHC staining of subcutaneous tumor tissues from mice previously downregulated by YTHDC1 suggested that YTHDC1 may promote EMT." (PMID 38573528, 2024). "The suppression of tumour proliferation observed in METTL3 KO may be mediated by YTHDC1, while the effect of METTL3 inhibition is mainly mediated by the YTHDF family." (PMID 39568154, 2024). "Indeed, we identified the reader YTHDC1 as one of the links between m6A modification and altered circRNA biogenesis in the tumor." (PMID 37019933, 2023). "Compared with advanced tumours, YTHDC1 expresses at higher levels in the T1 stage." (PMID 37070134, 2023).
tumor (continued). "As a consequence, RMS cell lines might have higher levels of m6A-modified RNA as well as an enhanced binding of YTHDC1, suggesting that they may promote the formation of circRNA species in the tumor." (PMID 37019933, 2023). "Moreover, we established a nude mouse xenograft model to demonstrate that GLUT3 knockdown blocked tumor growth and that the combined knockdown of GLUT3 and YTHDC1 attenuated the promoting effect of YTHDC1 silencing on tumor growth." (PMID 37258572, 2023). "Furthermore, the YTHDC1 overexpression enhanced the activity of caspase-3 but decreased the Ki-67 signaling in the tumor region as shown by IHC staining." (PMID 37781028, 2023). "The expression of YTHDC1 was only correlated with tumor purity, B cells, and macrophages." (PMID 35148766, 2022). "Notably, we found that YTHDC1 plays a greater role in promoting in vivo lung metastasis with a lesser effect on the growth of the primary tumor." (PMID 35966596, 2022). "In our study, we described in detail the regulatory mechanism of YTHDC1 in HNSCC tumor stem cells." (PMID 36411870, 2022). "Furthermore, ectopic expression of YTHDC1 partially rescued the miR-30d knockdown-induced tumor burden." (PMID 34021267, 2021). "Tumor immune-related genes YTHDC1, YTHDC2 and ALKBH5 were found." (PMID 34737950, 2021). "Moreover, YTHDC1 alone significantly reduced Panc-1 tumor growth and tumor weight in xenograft mouse tumor models, and vice versa." (PMID 34021267, 2021). "So far, we have proved that YTHDC1-induced miR-30d may function as a tumor suppressor gene by negatively regulating RUNX1 and its downstream glycolytic genes including HK1, and SLC2A1." (PMID 34021267, 2021). "Thus, our data revealed the critical tumor-suppressive roles of YTHDC1/miR-30d axis in PDAC development, with biological, mechanistic, and clinical impact on human PDAC and glycolysis pathways." (PMID 34021267, 2021). "These discoveries suggest that YTHDC1 might play a tumour suppressive role in early carcinogenesis." (PMID 37070134, 2023). "Therefore, in vitro experiments demonstrated that YTHDC1 promotes malignant tumor progression in HNSCC and may represent a poor prognostic indicator for patients." (PMID 36411870, 2022). "From the Sankey diagram, it was clear that RBM15, YTHDC1, and YTHDC2 were associated with more lncRNAs ― over 37% (147/397) ― indicating that these methylation-related enzymes have important catalytic and recognition roles in the occurrence of the tumor formation induced by ALV-J infection." (PMID 35529873, 2022). "Mechanistic interrogation in LIHC further reveals that YTHDC1 enhances m6A methylation of DCAF7 mRNA, leading to increased DCAF7 expression, which in turn amplifies Wnt/β‐catenin signalling and promotes tumour proliferation and migration." (PMID 41472554, 2026). "Together, these data suggest that m6A deposition on DCAF7 mRNA and its recognition by YTHDC1 cooperatively enhance DCAF7 expression, thereby linking RNA methylation machinery to oncogenic signalling in LIHC and potentially other tumour types." (PMID 41472554, 2026). "UMAP-based expression overlays revealed that NSUN2, YTHDC1, ALKBH5, ZC3H13, and TRDMT1 were predominantly expressed within epithelial clusters, consistent with a tumor-intrinsic regulatory role." (PMID 40565233, 2025). "LncRNA H19 can also competitively bind to miR-107, releasing YTHDC1 mRNA and interacting with YTHDC1 protein to modulate SRSF1 stability, eventually influencing IL-6 and IL-10 AS and driving tumor growth." (PMID 40032844, 2025). "YTHDC1 contributes to BC progression by regulating a feedback loop involving GLUT3 and RING finger 183, thereby enhancing glucose metabolism and advancing tumor development." (PMID 40747121, 2025). "There was a significant positive correlation between PKNOX1 expression and YTHDC1 and YTHDF3 expression in 27 tumor types." (PMID 40625743, 2025).
tumor (continued). "By analyzing the expression of YTHDC1 and ROD1 in the tissue array, we found that the YTHDC1 and ROD1 levels in tumor nuclei were positively correlated." (PMID 38573528, 2024). "Taken together, these data indicate that KAP1 interacts with YTHDC1 to regulate the stability of MYCN mRNA and sustain NB tumor malignancy." (PMID 38745192, 2024). "Knockdown of YTHDC1, POLR2B, and PBX1 reduced xenograft tumor volume and prolonged the survival of nude mice." (PMID 39090090, 2024). "Then, YTHDC1 enhanced the stability of FAM120A mRNA in an m6A-dependent manner, leading to the upregulation of FAM120A in resistant tumor cells." (PMID 38565940, 2024). "YTHDC1 has been shown to promote enhanced cyclization of circlGF2BP3 by METTL3 and increase PD-L1 expression in tumor cells." (PMID 39033180, 2024). "YTH N6-methyladenosine RNA binding protein C1 (YTHDC1), identified as a tumour-suppressing m6A reader, interacts with m6A modifications on the suppressor of cytokine signalling 4 (SOCS4) mRNA (Ref." (PMID 39377535, 2024). "Further mechanism studies elucidated that SLC12A5 bind with m6A reader YTHDC1 and in turn promotes the expression of transcription factor HOXB13 to promote tumour progression and castration resistance in an m6A-dependent manner." (PMID 37284313, 2023). "In this study, we found that the expression of m6A regulators was up-regulated in HCC tissues, and the up-regulated expression of YTHDF1/2, YTHDC1, RBM15 and METTL3 was significantly correlated with the tumour stage of HCC patients." (PMID 36434140, 2022). "METTL3, METTL14, METTL16, YTHDC1, YTHDC2, and ZC3H13 expression levels were significantly greater in tumor tissues (p < 0.05)." (PMID 36091006, 2022). "By comparing 50 normal and 374 tumor tissues, METTL14, YTHDC1, ZC3H13, ALKBH5, YTHDF2, and RBM15 had extremely lower expression in tumor tissues (p < 0.001)." (PMID 34277622, 2021). "It appeared that IGF2BP1/3, ELAVL1, HNRNPA2B1, HNRNPC, KIAA1429, RBM15, LRPPRC, FMR1, YTHDF1/2 are highly expressed in the tumor while FTO, METTL14/16, WTAP, YTHDC1 and ZC3H13 are down-regulated." (PMID 35095993, 2021). "In tumor immunity, YTHDC1, YTHDC2 and ALKBH5 were the most correlated regulatory factors of m6A with immune cell subtypes, and YTHDC1 and YTHDC2 were positively correlated with the selected anti-tumor immune genes." (PMID 34737950, 2021). "Except for KIAA1429, YTHDC1 and WTAP, the remaining 10 m6A methylation regulators were differentially expressed between normal and tumor tissue." (PMID 33995635, 2021). "YTH Domain Containing 1 (YTHDC1) is one of the m6A readers that is essential for oocyte development and tumor progression." (PMID 33188203, 2020). "Particularly, in contrast to their low CNV frequencies (< 5%) in normal samples, CBLL1, METTL14, RBM15, IGF2BP1, YTHDC1, and YTHDF2 exhibited more than 20% difference in their frequencies of CNVs between tumor and normal samples." (PMID 33585234, 2020). "Comparisons between adjacent normal and tumor samples identified seven down-regulated (METTL14, WTAP, YTHDC1, YTHDC2, ALKBH5, FTO, and YTHDF2) and one up-regulated (YTHDF1) regulators." (PMID 32500031, 2020). "We show that metadherin modulates alternative splicing via interactions with known splicing factors YTHDC1, Sam68 and T-STAR, potentially revealing novel tumour biomarkers and therapeutic targets." (PMID 31450747, 2019). "Taken together, these data demonstrate that YTHDC1 regulates SMAD6 expression in UCB in a m6A-dependent manner and thus reveal a mechanism through which downregulation of an epitranscriptomic reader can promote tumor invasiveness." (PMID 39741187, 2025). "CircRNAs themselves have been implicated in oncogenic processes in RMS, and the study by Dattilo and colleagues provides important mechanistic insights by demonstrating that YTHDC1 and DDX5 act cooperatively to drive the biogenesis of tumor-promoting circRNAs in this context." (PMID 40950397, 2025).
tumor (continued). "In further experiments, we identified tumor areas in UCB tissue sections via H&E staining and then used simultaneous RNA fluorescence in situ hybridization (FISH) and immunofluorescence (IF) to detect SMAD6 mRNA and YTHDC1 protein, respectively." (PMID 39741187, 2025). "The RNA N6-methyladenosine (m6A) reader YTHDC1 regulates RNA splicing, nuclear transport, and mRNA stability and is a potential tumor target; however, its ubiquitin E3 ligase has not been described." (PMID 40133252, 2025). "Unfortunately, romidepsin and T417 as tumor targeting drugs and targeting the YTHDC1/circPOLR2B/POLR2B/PBX1 axis were not examined in the present study." (PMID 39090090, 2024). "Considering that the depletion of YTHDC1/DDX5 reduces cell proliferation and that many circRNAs are involved in the control of cell growth, we speculate that the modulation exerted by YTHDC1 and DDX5 may act as an oncogenic feature in this tumor." (PMID 37019933, 2023). "The results showed significant differences in the expression of almost all m6A regulators between tumor and normal tissues, with the majority of m6A regulators being upregulated in WT tissues (P < 0.001), while ALKBH5 and YTHDC1 were downregulated in WT expression levels." (PMID 37735424, 2023). "YTHDC1, HNRNPC, HNRNPA2B1, YTHDF1, YTHDF2, and YTHDF3 all showed significantly high expression in ccRCC (all p-values < 0.0001) compared to the average overall gene expression in the tumour tissue." (PMID 36899967, 2023). "Conversely, YTHDC1 KO in TNBC cells (MDA-MB-231) resulted in significantly decreased number and size of lung metastases in xenograft recipient mice and resulted in a moderate decrease in primary tumor size compared to control mice." (PMID 35966596, 2022). "In addition, YTHDC1, YTHDF1, YTHDF2, IGF2BP3, HNRNPA2B1 and NKAP were confirmed by two databases to be positively correlated with tumor stage, which deserved more attention in the treatment of HCC." (PMID 35963644, 2022). "Consistent with the in vitro study results, silencing YTHDC1 expression in SCC9 cells dramatically retarded tumor growth compared with the control cells in nude mice, as confirmed by the measurement of tumor volume and tumor weight." (PMID 36411870, 2022). "Moreover, YTHDC1 was negatively modulated by EMP3, partly through Akt signaling, which was determined a tumor suppressor and inhibited DNA replication, DNA damage repair, chemotherapeutic drug resistance, stem-like properties and Akt-mTOR signaling activation." (PMID 35501308, 2022). "Notably, we found that YTHDC1 mRNA expression levels were significantly and positively correlated with those of BMI1 and SOX2, which are HNSCC tumor stem cell-specific indicators." (PMID 36411870, 2022). "Further, we also found the m6A methylation-related genes FTO, IGF2BP3, and YTHDC1 might participate in the process of PGM1 methylation modification, thereby affecting tumor progression and metastasis." (PMID 35251177, 2022). "In summary, our results suggest that one of the tumor-suppressive effects of increased expression of miR-30d is to inhibit RUNX1 and inactivate the aerobic glycolysis signaling, forming a vigorous YTHDC1-miR-30d-RUNX1-SLC2A1/HK1 axis to repress PDAC occurrence and progression." (PMID 34021267, 2021). "Most increased regulators in tumor cases compared to normal cases were YTHDF2 (p < 0.001), FTO (p < 0.001), YTHDC1 (p < 0.001), YTHDC2 (p < 0.001), YTHDF1 (p < 0.001), KIAA1429 (p < 0.001), METTL3 (p < 0.010), WTAP (p < 0.001), RBM15 (p < 0.001), HNRNPC (p < 0.001), and ALKBH5 (p = 0.001)." (PMID 32733931, 2020). "Collectively, YTHDC1 or RBM15 condensates dispersed in the nucleus have made great contributions to the stabilization of the oncogenic transcripts, thereby promoting tumorigenesis, and future anti-tumor strategies can inhibit the formation of these condensates." (PMID 39239525, 2024).